BEST4 (bestrophin 4)
Description:
Ligand-gated anion channel that allows the movement of anions across cell membranes when activated by Calcium (Ca2+). Mediates the movement of hydrogencarbonate and chloride.
Synonyms: VMD2L2
Tractability: Antibody: UniProt places it where antibodies can reach, with medium confidence; UniProt predicts a signal peptide or a membrane-spanning region; its Gene Ontology location is reachable by antibodies, with medium confidence.
Gene: Protein-coding gene on chromosome 1 (44,781,836 to 44,791,550, reverse strand). Ensembl gene ENSG00000142959.
Subcellular location: Cell membrane
Pathways (Reactome):
Transport of small molecules: Stimuli-sensing channels
Gene Ontology:
Molecular function: bicarbonate channel activity; chloride channel activity; intracellularly calcium-gated chloride channel activity; channel activity
Biological process: chloride transmembrane transport; bicarbonate transport
Cellular component: plasma membrane
Genetic constraint (gnomAD): Loss-of-function variants: 37 observed, 46.13 expected, observed/expected ratio (o/e) 0.8, 90% interval 0.62 to 1.05. The upper end of that interval is the gene's LOEUF score, 1.05, which puts it in group 4 of 6, group 1 being the genes least tolerant of losing a copy. Missense variants: 549 observed, 577.33 expected, observed/expected ratio (o/e) 0.95, 90% interval 0.89 to 1.02. Synonymous variants: 250 observed, 235.72 expected, observed/expected ratio (o/e) 1.06, 90% interval 0.96 to 1.18.
Homologues: Orthologues: chimpanzee BEST4 (100% identical), macaque BEST4 (99% identical), rabbit BEST4 (92% identical), pig BEST4 (92% identical), dog BEST4 (91% identical), guinea pig BEST4 (84% identical), rat Best4 (81% identical), tropical clawed frog best4 (68% identical), zebrafish best4 (51% identical), Drosophila melanogaster Best1 (41% identical), Drosophila melanogaster Best4 (39% identical), Drosophila melanogaster Best3 (37% identical), and 17 more. Paralogues in human: BEST2 (55% identical), BEST3 (51% identical), BEST1 (50% identical).
Diseases named in the same sentence as BEST4 in open-access papers:
BEST4 is named in the same sentence as 18 diseases in open-access papers, as found by Europe PMC text mining. Sharing a sentence is not in itself a finding about the gene and the disease. The quoted sentences say what the papers report.
colorectal cancer (9 papers, 2019 to 2025). A primary or metastatic malignant neoplasm that affects the colon or rectum. "In colorectal cancer and inflammation loss of BEST4/OTOP2 cells has been described." (PMID 37543577, 2023). "In a multi‐omics study of colorectal cancer, Tuzzerel was also the microbiol genus that was most associated with other genes and metabolites, including a negative association with serum uric acid levels and the expression of BEST4 and DGKB genes." (PMID 38107095, 2023). "In this study, we demonstrate that BEST4 overexpression attenuates cell proliferation, colony formation, and mobility in colorectal cancer (CRC) in vitro, and impedes the tumour growth and the liver metastasis in vivo." (PMID 39699952, 2024). "BEST4 inhibits colorectal cancer (CRC) cell proliferation, clonogenesis, migration, and invasion in vitro." (PMID 39699952, 2024). "BEST4 deters epithelial-to-mesenchymal transition (EMT) in colorectal cancer (CRC) in vitro and in vivo." (PMID 39699952, 2024). "Although the role of BEST4+ cells in gut health remains unclear, they are believed to play a role in maintaining intestinal homeostasis since excess BEST4 activity may lead to the progression and metastasis of colorectal cancer." (PMID 40936409, 2025). "BEST4 relays the HES4 signal and downregulates TWIST1 expression to counteract epithelial-to-mesenchymal transition (EMT) induction in colorectal cancer (CRC)." (PMID 39699952, 2024).
colon cancer (3 papers, 2020 to 2023). "The expression of bestrophin 4 (BEST4) is decreased in colon tumor, colon adenocarcinoma and rectal adenocarcinoma and CRC." (PMID 35114976, 2022). "The TCGA results indicated that SPIB, KRT24, PHLPP2, PLP1, BEST4, CA7, and C11orf86 were all downregulated, while KRT80, SLC39A10, AJUBA, FOXQ1, and CLDN1 exhibited upregulated levels in colon cancer." (PMID 32633726, 2020).
adenoma (2 papers, 2010 to 2024). A neoplasm arising from the epithelium. "Further validation by qPCR in the paired tissues of 50 colorectal adenomas and 124 CRC showed that the BEST4 was expressed significantly less in adenomas and tumours than in ANTs." (PMID 39699952, 2024). "(C) Expression levels of BEST4 mRNA in 50 pairs of adenoma tissues compared with ANTs." (PMID 39699952, 2024).
cystic fibrosis (2 papers, 2024 to 2026). Autosomal recessive disorder caused by pathogenic variants in the CFTR gene (cystic fibrosis transmembrane conductance regulator), which encodes a chloride and bicarbonate channel expressed in epithelial cells, and follow the diagnosis criteria. "The expression of CFTR in BEST4+ cells in the large intestine may have important implications to understand epithelial fluid efflux, regulation of mucus viscosity, and for the management of cystic fibrosis or diarrheal disease." (PMID 40907661, 2026).
inflammatory bowel disease (2 papers, 2024 to 2025). A spectrum of small and large bowel inflammatory diseases of unknown etiology. "A few studies suggested that BEST4+ cell homeostasis could be disrupted in inflammatory bowel diseases (IBD), including ulcerative colitis (UC) and Crohn’s disease (CD)." (PMID 38557358, 2024).
Hypoalbuminemia (1 paper, 2024). The concentration of albumin in the blood circulation is below the lower limit of normal. "Downregulation of BEST4 cells and goblet cells indicates intestinal epithelial barrier damage and dysregulation of ion transmembrane transport, which may be associated with protein loss-associated hypoalbuminemia and diarrhea in CCS patients." (PMID 38297356, 2024).
lymph node metastasis (1 paper, 2024). "We further evaluated the clinicopathological significance of BEST4 expression in CRC patients by examining its correlation with gender, tumour-node-metastases stage, and lymph node metastasis based on the eighth edition of the American Joint Committee on Cancer Staging Manual." (PMID 39699952, 2024).
tumor (6 papers, 2019 to 2025). "We observed that there were twofold greater of the liver metastatic nodules in the BEST4 deficient tumours than the control." (PMID 39699952, 2024). "In cancer cell cultures and mouse tumour xenografts, the present study shows that BEST4 inhibits the development of CRC." (PMID 39699952, 2024). "Conversely, knockout of BEST4 using CRISPR/Cas9 in CRC cells revitalises tumour growth and induces EMT." (PMID 39699952, 2024). "Essentially, the sizes and weights of tumours in BEST4 overexpression group were only half of the EV control, in conjunction with the similar magnitude reduction of Ki67+ cells as analysed by immunohistochemistry." (PMID 39699952, 2024). "Further analysis of the HCT116 tumour tissue lysates showed that BEST4 deterred EMT by upregulating E-cadherin, and downregulating VIM and TWIST1." (PMID 39699952, 2024). "Colonocytes highly expressing BEST4 were enriched in adjacent tissues, whereas BEST4low colonocytes exhibited tumor preference." (PMID 34185431, 2021). "In the present study, significant down regulation of BEST4 was found in tumor issues of CRC patients." (PMID 31024853, 2019). "These pro-tumour effects on HCT-15 were also reversible when BEST4 expression was rescued." (PMID 39699952, 2024). "Because EMT initiation is a critical process in tumour progression, we evaluated the effect of BEST4 on EMT using quantitative polymerase chain reaction (qPCR) and found that BEST4 expression upregulated CDH1 and TJP1 and downregulated VIM and TWIST1 in HCT116 compared with the control (p<0.05)." (PMID 39699952, 2024). "To evaluate the effect of BEST4 on tumour growth, we constructed BEST4-expressing HCT116 and Caco2 CRC cell lines and showed that BEST4 overexpression halved cell proliferating rates of their respective empty vector (EV) controls when they were monitored in live and analysed using InCucyte." (PMID 39699952, 2024). "Given the co-expression of BEST4+ and HES4+ in a human colonic epithelial lineage, we sought to investigate their biological interactions during tumour growth." (PMID 39699952, 2024). "However, if the role of BEST4 is involved in regulating tumour progression remains largely unknown." (PMID 39699952, 2024).
cancer (2 papers, 2022 to 2024). A tumor composed of atypical neoplastic, often pleomorphic cells that invade other tissues. "The genes—including BEST4, LMO1, ARID3C, TMEM44, FKBP10, and TRIB3—were correlated with VSX1 and might play a primary role in the transcriptional misregulation of cancer from the TCGA database." (PMID 36463181, 2022).
BEST4 also shares sentences with these, for which no sentence is quoted: diarrheal disease (2 papers); autoimmune enteropathy (1); colon adenocarcinoma (1); colonic polyps (1); colorectal adenoma (1); infection (1); Obesity (1); rectal adenocarcinoma (1); ulcerative colitis (1).